IL10 (interleukin 10)
Diseases named in the same sentence as IL10 in open-access papers (continued):
Sharing a sentence is not in itself a finding about the gene and the disease.
infection (continued). "PrimePCR array analysis of hNS/PCs showed that the mRNA levels of inflammatory cytokine related genes (IL-1A, TNFα, IL28A, IL29, NF-KB2), chemokines (CSF2, CCL3, CCL4, CXCR3),TLRs (TLR3, TLR8), IL-10, and Casp9 were all reduced in the Smaducin-6 treated group following ZIKV-FSS13025 infection." (PMID 32544190, 2020). "Therefore, secondary abiotic IL-10−/− mice were perorally infected with C. jejuni and treated with synthetic PACAP38 intraperitoneally from day 2 until day 5 post-infection." (PMID 33007819, 2020). "After 96 h, 2 and 10 weeks of infection lung leukocytes were obtained from infected AhR−/− and WT mice and analyzed by flow cytometry for the presence of intracellular cytokines (IL-12, TNF-α, IL-1β, IL-6, TGF-β and IL-10) in CD11c+ gated cells." (PMID 32647342, 2020). "Comprehensive studies investigating serum IL-10 levels and its association with post-SAH infection, immunodepression and clinical outcome are lacking." (PMID 32106601, 2020). "In mice experimentally infected with L. infantum, infection control in the absence of IL-10 was found to be regulated by IL-17." (PMID 32966326, 2020). "In later stages of infection when NA is not present, IL-10 exhibits immunosuppressive properties and protects the host from excessive tissue damage." (PMID 32974217, 2020). "The secretion of IL-10 from CD4+ CD25− FOXP3− cells in the initial phase may suppress the Leishmanicidal mechanisms of macrophages, which supports the establishment of infection." (PMID 32849534, 2020). "The possible reason is that the basic function of IL‐10 is to reduce cytokines produced by TH1 cells, which play a role in immunosuppression with anti‐inflammatory activity, and cannot reflect the degree of infection in the early stages of inflammation." (PMID 33025767, 2020). "The blood sera exhibited substantial decrease in IFN-γ and increase in IL-17 levels but no alteration in IL-10 levels regardless of infection dose in C. krusei-infected group compared to the non-infected group." (PMID 33552998, 2020). "Nonetheless, neither specific antibodies, nor increased secretion of IFNγ, IL-4, and IL-10 cytokines, conferred greater protection against infection." (PMID 32916868, 2020). "The cytokine IL-27 that is also considered to be an IL-10 regulator, did not affect IL-10 production during infection." (PMID 32655552, 2020). "Patients who developed an infection yielded significantly lower TNF-α values (86 vs 192 pg/mL, p = 0.030) and a trend towards higher IL-10 values (122 vs 84 pg/mL, p = 0.071) following ex vivo whole blood stimulations when compared to patients not developing an infection." (PMID 33237337, 2020). "Paradoxically, in L. mexicana and L. amazonensis, IL-10 had little effect on lesion outcome as infected IL-10-/- BALB/c failed to control infection." (PMID 33415318, 2020). "The bacterial components and signaling pathways that lead to induction of IL-10 following infection with Δhly L. monocytogenes have not been experimentally addressed." (PMID 32634175, 2020). "However, DDA/TDB also induced the highest level of IL-10 responses to the antigen CMFO before and after infection of all groups." (PMID 33117374, 2020). "As a key regulatory cytokine, IL-10 may suppress over-expression of IFN-γ and TNF-α while permitting an immune response robust enough to eradicate infection." (PMID 32411624, 2020). "Our observation reveals higher expression of IL‐10 and MDR1 along with PP2A upon LdR infection." (PMID 32031337, 2020). "Although PBMC proliferation, IFN-γ and IL-10 production correlate with infection, they do not correlate with protection." (PMID 32487248, 2020).
infection (continued). "At 3 h post infection, both viable and heat-killed APEC strongly up-regulated gene expression of pro-inflammatory cytokines IL-1β and IL-6, chemokine IL-8 and the anti-inflammatory cytokine IL-10 compared to control cells that were mock-treated with medium." (PMID 32972448, 2020). "Neutralizing TGF-β did not alter the course of P. yoelli 17XL infection, likely because of compensatory increases in the anti–inflammatory cytokine IL-10." (PMID 32043415, 2020). "Several IL-10 producing Breg cell subsets such as transitional type 2- marginal-zone precursor (T2-MZP) cells, CD5+CD1dhi B cells, Tim-1+ B cells, plasma cells, and plasmablasts have been reported in various infection and inflammation conditions." (PMID 32849556, 2020). "Interleukin 12 (IL-12p70) and interferon γ (IFNγ) increased in blood during early infection; acute infection was marked by elevated circulating natural killer (NK) cells, neutrophils, and B cells, as well as increased tumor necrosis factor (TNF) and IL-10." (PMID 33021470, 2020). "For teleosts, which rely on non-specific immune processes to enhance their immune response and resist pathogen infection, cytokines such as TNF-α, IL-1β, IL-6, IL-10, IL-12, and TGF-β, primarily produced by activated macrophages, also play an important role in the immune system." (PMID 32457762, 2020). "Importantly, vaccination of mice with rBmSP44 resulted in a Th1/Th2 mixed immune response with significantly elevated IL-10 and IFN-γ levels during the early stage of infection." (PMID 32733477, 2020). "During the chronic stage of infection (8 weeks), cytokine levels in Cbs+/− and WT mice were similar except for a lower TNF-α and IL-10 levels in Cbs+/− mice, which might be due to reduced percentages of neutrophils and lymphoid cells mostly in the spleen." (PMID 31992699, 2020). "Here, serum IL-6 and TNF levels in mice were not affected, however IL-10 was attenuated at 14 d post-infection." (PMID 32482929, 2020). "The infection with S. Typhimurium induced the appearance of all inflammatory cytokines in blood plasma and allowed to count the IL-10/TNF-α ratio in contrast to all groups of non-infected piglets with nonmeasurable cytokines." (PMID 33333934, 2020). "infection of SCC cells did not affect mRNA levels of IL10, IL1β, IL1α, HBEGF, and GMCSF, compared with NS cells." (PMID 31912662, 2020). "In addition, an increase in TNF-α, IL-6, IL-10 and VEGF levels were measured at 6 h and 24 h post infection." (PMID 32316163, 2020). "Yet, TIGIT modulation did not affect overall numbers of IL-10-Thy1.1+ T cells in the spleen in any of the infection models." (PMID 32152316, 2020). "IL-10 expression in C57BL/10 infected mice was significantly upregulated during the experiment, while IL-4 expression was upregulated in this group only at 30 days after infection." (PMID 32983013, 2020). "As infection persisted, we observed an increase in the cytokine TNFα; a decrease in the cytokine IL-6; an increase in T-cell priming co-receptors CD80/86, and MHCII; and a decrease in CD103 and IL-10." (PMID 32635236, 2020). "We further studied the degranulation of these cells after contact/infection with ZIKV by measuring β-hexosaminidase release as well as the expression profiles of TNF-α (tumor necrosis factor-α), IL-6 (interleukin-6), IL-10 (interleukin-10) and VEGF (vascular endothelial growth factor)." (PMID 32316163, 2020). "Kinetics of cytokine production, including TGF-β, IL-10, IFN-γ, and TNF-α have been linked to the differential outcomes in infection with lethal and non-lethal P. yoelli, which starkly diverge within the first few days of infection." (PMID 32043415, 2020). "In the present work, samples obtained after 45 days of infection revealed that diabetic mice still presented signs of strong ongoing inflammation, characterized by high IFN-γ levels and a high TNF-α:IL-10 ratio, whereas this inflammation was found to be subsided in the nondiabetic groups." (PMID 33312173, 2020).
infection (continued). "Therefore, secondary abiotic IL10-/-, and TLR4-/- IL10-/-, mice were subjected to peroral human FMT on three consecutive days, one week prior to infection." (PMID 32443576, 2020). "We observed that higher IL‐17A, IL‐10 and sE‐selectin levels identify patients with IE infection foci (diagnosed by TEE or TTE imaging) when compared to extravascular infections, while the other five biomarkers, available risk factors or clinical data did not (P > 0.05, data not shown)." (PMID 32082571, 2020). "Compared to patients without an infection, a trend towards higher IL-10 values at baseline was found in infected patients (122 vs 84 pg/mL, p = 0.071)." (PMID 33237337, 2020). "In experimental infection with L. donovani, the absence of IL-10 resulted in the control of parasite replication, but also caused tissue damage and the rupture of splenic microarchitecture." (PMID 31608245, 2019). "Noticeably, PC1 mostly segregated the non-infected vs. infected populations and PC2 distinguished the infection parameters (infection index, percentage of infection, oxidative burst, Elastase, and MPO) vs. the cytokines IL-6, IL-10, IL1-β, and TNF-α production." (PMID 31134162, 2019). "Our data revealed that 14 weeks post-infection, HisAK70-vaccinated mice showed key biomarkers of protection, such as higher iNOS/arginase activity, IFN-γ/IL-10, IFN-γ/IL-4, and GM-CSF/IL-10 ratios, in addition to an IgG2a-type response when compared to the control group." (PMID 31739549, 2019). "TNF-α was expressed at the same level regardless of live, inactivated, or dead MAH infection; however, the expression of IL-12p70 and IL-10 was confirmed to be induced during the infection of live MAH." (PMID 31440223, 2019). "IL-10 was not significantly altered regardless of when alcohol was administered prior to infection in lung or spleen tissue." (PMID 31821337, 2019). "In the process of inducing IL-10 expression, PCV2 Cap plays a pivotal role in the early phase of infection, whether PCV2 Rep protein is also involved in the regulation of IL-10 expression during PCV2 infection remains unknown." (PMID 31835539, 2019). "Our data suggest that higher levels of TNF- α between days 4 and 11 post-infection were responsible for this imbalance, whereas a number of field studies attribute this imbalance to lower levels of IL-10 in SMA rather than an increase in TNF-α46,75." (PMID 31831787, 2019). "Hpb-infected mice demonstrated marked increase of helminth antigen-specific IgG1, IgA and IgE but not IgG2a antibody responses after 9 weeks of infection, concomitant with an increase of systemic IL-10 and IL-6 levels." (PMID 30685251, 2019). "However, although IL10 siRNA resulted in elevated TNF and IFNG mRNA levels during G18 infection, they remained significantly lower than that measured during AF2122/97 infection." (PMID 31527895, 2019). "There was no significant Ag85B-specific IL-10 production in any of the immunized groups after the infection." (PMID 30849108, 2019). "Our results show that infection with this protozoan influences the peripheral and placental immune response and that it is mediated by a mixed of Th1 (IFN-γ and TNF-α), Th2 (IL4) and Treg (IL10) cytokines." (PMID 31533826, 2019). "Furthermore, at 8 weeks post-infection, the percentage of splenic CD4+ T cells showing the potential to secrete IL-10 was significantly and tendentiously increased in BALB/c and SV129 mice, respectively." (PMID 30881923, 2019). "From our study, GM-CSF and modulating cytokines TNF-α and IL-10 were suppressed in mice administered alcohol 0.5 or 3 h prior to infection, compared to mice not administered alcohol." (PMID 31821337, 2019). "Similar to IL-10, elevated levels of transforming growth factor β (TGF-β), another anti-inflammatory cytokine, have been shown to correlate with the severity of injury and the development of secondary infections." (PMID 31014397, 2019).
infection (continued). "Maternal infection was associated with a 7% lower CRP level (95% CI, − 17,5%) among offspring compared with offspring born to women without an infection and similarly an 8% lower level of IL-6 (95% CI -15,1%), and a 9% lower level of IL-10 (95% CI, − 23,20%)." (PMID 30923624, 2019). "Further, we found the levels of IL-4, IL-10 and IL-13 were not elevated in response to rosiglitazone treatment during super-infection." (PMID 31159430, 2019). "For whipworm, the data suggests that the focal damage generated by infection only becomes a significant problem in the absence of IL-10 signalling and/or following very heavy infections." (PMID 30640950, 2019). "Functionally, an absence of IL-10 in mice exacerbates the host’s ability to control bacterial colonization during the innate phase of infection in the bladder." (PMID 31776239, 2019). "Except for Hsd3b1, infection with S. haematobium did not have an influence on Vitamin D pathway associated (VDR, Cyp27b1) or immunological (IL10, IFNG, Foxp3) genes as well as vitamin D plasma levels." (PMID 31673046, 2019). "As with the investigated pro-inflammatory cytokines, NOS2 mRNA levels were significantly higher, with on average 2.7 times more NOS2 mRNA (p < 0.001) being detected, during G18 infection in the absence of IL10." (PMID 31527895, 2019). "The possible participation of IL-10 producing B cells in the prevention of fetal damage or death after infections has not been explored in deep." (PMID 31249364, 2019). "In contrast to the effect of IL10 knock-down during G18 infection of bMDM, IL1B and IL6 mRNA levels were not significantly affected by IL10 knock-down during AF2122/97 infection." (PMID 31527895, 2019). "After infection of Sk29Mel-1 with H-1PV, there was no significant change in the level of IL-10 but a decrease in the levels of TGF-ß was detected." (PMID 31192129, 2019). "In contrast to the clear MyD88-dependence of these chemokines and IFNγ-response genes, the induction of the immunoregulatory cytokine IL-10 and of the enzyme Arginase-1 by NMII was largely independent of MyD88, which contrasts to the results obtained with BMM after infection with NMII in vitro." (PMID 30800124, 2019). "In V. vulnificus-infected fish, Epinecidin-1 could also regulate immune response genes such as IL-10, IL-1b, TNF-α, and IFN-γ and help to control the infection by enhancing the immunity." (PMID 31138331, 2019). "Albeit not statistically significant, the levels of G-CSF, IL-1α, MCP-1/CCL2, MIP-2/CXCL2 at day 1, G-CSF, KC, MCP-1, and MIP-2 at day 2, and IL-1α, IL-1β, IL-6, IL-10, MCP-1, MIP-2, and TNF at day 3 post-infection were 1.5–4.4-fold higher in SIRT3/5−/− than in SIRT3/5+/+ mice." (PMID 31632409, 2019). "IL-10 levels decreased (albeit not significantly) at 6 h and 30 h after infection, and increased significantly at 3–6 dpi, and IL-17A levels decreased significantly at 6 dpi, and significantly increased at 30 h and 3 dpi." (PMID 31855175, 2019). "In addition, we found that infection with EIB202 induced the expression of TNF-α and IL-10 transcripts, which was further enhanced in zebrafish larvae infected with Δtrxlp." (PMID 31314784, 2019). "Thus, the low level of IL-10 production as well as the high ratios of IFN-γ/IL-10 and TNF/IL-10 in vaccine groups confirmed again switching to Th1, and this response is probably involved in controlling the infection." (PMID 31014347, 2019). "Similarly, treatment of bMDM with IL10 siRNA enhanced expression of IL1B, TNF, IL6, IFNG and NOS2 induced by G18 infection." (PMID 31527895, 2019). "We have shown that upon infection with whipworms, signalling by IL-10, but not IL-22 or IL-28, is crucial for the resistance to colonization by opportunistic pathogens, control of host inflammation, intestinal barrier maintenance and worm expulsion." (PMID 30640950, 2019).
infection (continued). "Although not statistically significant, IL-10 was lower in mice administered alcohol 6 or 24 h prior to infection compared to alcohol administration 0.5 or 3 h prior to infection." (PMID 31821337, 2019). "The clinical signs, together with the pattern of increased TNF-α, IL-6, IL-12, IL-10 and IL-17 mRNA level observed in BVDV2-infected goat PBMCs in this study, suggested that BVDV-2 induced an acute inflammatory response in the early stage of infection." (PMID 31226933, 2019). "Consistent with previously published research, the secretion of IL-10 (a key inflammatory mediator IL-10) was absent during the early stages of infection with all 3 pathogens." (PMID 31546628, 2019). "Finally, at this later time-point post-infection, CD8+ T cells from infected BALB/c mice maintained their capacity to secrete IL-10." (PMID 30881923, 2019). "Production of 8 cytokines and chemokines was reduced in mice upon ponatinib treatment at day 5 post-infection, whereas the concentrations of IL-6, IL-10, MCP-1, Eotaxin, IL-12 (p40), and MIP-1β were not affected." (PMID 31293574, 2019). "The infection induces acute peritoneal recruitment of neutrophils and other innate immune cells, and the local and systemic production of proinflammatory cytokines and chemokines (IL-1β, IL-5, IL-6, TNF-α, RANTES, MIP-1β, MCP-1, KC and IL-10)." (PMID 31024025, 2019). "In contrast, we observed significantly enhanced expression of Cxcl1 (KC), Il6, and Il17, but not of Cxcl2 (MIP-2), Ifng, or Il10, in the huLangerin group as opposed to WT controls after infection with the S. aureus ΔtarM mutant." (PMID 31088921, 2019). "Immunization and/or infection did not alter cytokines IL-2, IL-4, IL-10, IL-17, IFN-γ, and TNF-α levels; however, IL-6 significantly (p < 0.05) increased, as compared with untreated control." (PMID 31065302, 2019). "Therefore, IL10 appears to regulate NO production by different mechanisms during AF2122/97 and G18 infections." (PMID 31527895, 2019). "Consequently, we analyzed the mRNA levels of the proinflammatory cytokines TNF-α, IL-1β, and IL-6 and the anti-inflammatory cytokine IL-10, as well as the antimicrobial peptides TAP, DEFB1, and BNBD5 in LEAS-pretreated bMECs before and after infection." (PMID 31612151, 2019). "In the context of HSV-2 infection, we did not detect a significant alteration in IL-10 levels from WT vaginal lavages between different days post-infection." (PMID 31214198, 2019). "We observed that infection of macrophages with BCG increased the IL-10 promoter activity by ~8.0 folds in comparison with non-infected cells (p = 0.0010)." (PMID 31921181, 2019). "In contrast, after infection, the F3 vaccine induced the strongest IFN-γ and TNF-α secretion, while the chimera, followed by the F3 and NH36 vaccines, was still predominant for the production of IL-10." (PMID 31024556, 2019). "However, the investigation of this polymorphism, together with others located in the IL10 gene, showed that IL10 −819*C/T and −592*C/A polymorphisms may contribute to susceptibility to infection by HTLV-1, although it does not appear to be related to the protection against HAM development." (PMID 31652745, 2019). "We next monitored IL-10+CD19+ and IL-10+CD3+ cells at different time points after infection." (PMID 30881362, 2019). "Consistent with our previous observations in LdWT and LdCen−/− infections in mice, there was a slightly lower but not significant difference in the IL-10 level (p = 0.135)." (PMID 31608064, 2019). "Filarial infection in Malian children aged between 11 and 17 years was found to have a higher ex vivo frequency of CD4+ cells producing IL-10 and IL-4 compared with those without the infection." (PMID 29970128, 2018). "IL-6, IL-10 and G-CSF showed smaller, non-significant elevations in R. felis mono-infection when compared to healthy controls." (PMID 29736763, 2018). "For TGF-β and IL-10 there was no statistical difference between the groups during the infection period." (PMID 30564201, 2018).